LPL (lipoprotein lipase)
Diseases named in the same sentence as LPL in open-access papers (continued):
Sharing a sentence is not in itself a finding about the gene and the disease.
dyslipidaemia (19 papers, 2009 to 2025). "Dyslipidaemia caused by hyperglycaemia is linked to impaired liver Apo production, which affects lipoprotein lipase and cholesterol ester transport protein activities, leading to atherogenic changes." (PMID 40375303, 2025). "Excess GCs cause dyslipidaemia due to inhibition of lipoprotein lipase (LPL) activity in adipose tissue." (PMID 39202522, 2024). "The most promising genetic variant in this context is a mis-sense mutation, Asn291Ser, in LPL which correlates with lowered LPL activity and increased dyslipidaemia in two separate studies." (PMID 21429808, 2011). "Dyslipidaemia is a hallmark of the syndrome and is associated with a whole body reduction in the activity of lipoprotein lipase (LPL), an enzyme under the regulation of the class of nuclear receptors known as peroxisome proliferator-activated receptor (PPAR)." (PMID 20670429, 2010). "Indeed, estrogen deficiency increases lipoprotein lipase activity, leading to blood fatty acids accumulation, and thus dyslipidaemia." (PMID 34630615, 2021). "Changes in LPL gene activity may influence the risk of dyslipidaemia and vascular complications." (PMID 41234028, 2025). "These must have interrupted insulin action on their tissues, reduced lipoprotein lipase and facilitated peripheral tissues lipolysis, which undoubtedly hastened dyslipidaemia and hyperglycemia in the sedentary rats." (PMID 36434695, 2022). "This form of dyslipidaemia is attributable to down-regulation of lipoprotein lipase enzymes which are found principally in skeletal muscle, myocardium and adipose tissue." (PMID 34394802, 2021). "The study has demonstrated the existence of SNPs in LCAT and LPL among HIV-infected individuals with dyslipidaemia in Ghana." (PMID 33173066, 2020). "It was demonstrated in the study that QSYQ decreases plasma TC, TG, and LDL levels and up-regulate LPL expression and plasma HDL levels, which effectively ameliorated dyslipidaemia and decreased AMI risk." (PMID 28303103, 2017). "In fact, IR seems to contribute to dyslipidaemia partly through lipolysis stimulation and altered expression of lipoprotein lipase and hepatic lipase." (PMID 25995732, 2015). "Stimulation of LPL activity by either the use of transgenic overexpression or the administration of LPL-raising drugs has been shown to ameliorate the observed dyslipidaemia." (PMID 20670429, 2010). "Furthermore, n-3 PUFA, abundant in fresh vegetables and aquatic products, can regulate lipoprotein lipase activity, thereby improving dyslipidaemia." (PMID 40823030, 2025). "Dyslipidaemia is a well-known dose-dependent adverse effect of mTOR inhibitors that is thought to occur through down-regulation of low-density lipoprotein receptors and inhibition of lipoprotein lipase activity." (PMID 26020944, 2015). "IH has also been shown to play an important role in inhibiting LPL activity and increasing ANGPTL4 levels, leading to dyslipidaemia." (PMID 30524367, 2018). "The increased catabolism of TAG-enriched VLDL by LPL may thus serve to positively re-modulate HDL and LDL profile in dyslipidaemia." (PMID 19638239, 2009). "In conclusion, GA may be a potential compound in improving dyslipidaemia by selectively inducing LPL expression in non-hepatic tissues." (PMID 20670429, 2010). "Yet, dyslipidaemia may not independently occur as it may be worsened by single nucleotide polymorphisms (SNPs) in lecithin cholesterol acyltransferase (LCAT) and lipoprotein lipase (LPL)." (PMID 33173066, 2020).
Hyperglycemia (19 papers, 2011 to 2025). An increased concentration of glucose in the blood. "Long-term hyperglycaemia could cause damage to blood vessel endothelium in the whole body, reducing lipoprotein lipase activity, the increase of the TG level and the decrease of HDL concentration." (PMID 30110438, 2018). "We defined a model where only a fraction of the binding sites at the luminal side of coronary EC are occupied by LPL, and hyperglycemia leads to rapid filling of the unoccupied sites." (PMID 34356640, 2021). "Thus, acute insulin resistance following administration of dexamethasone or hyperglycemia and hypoinsulinemia in rats injected with 55 mg/kg STZ (D55) causes a significant increase of heparin-releasable LPL at the coronary lumen." (PMID 39081272, 2024). "Intravenous insulin is a non-invasive treatment by increasing activation of lipoprotein lipase (LPL) to accelerate chylomicron breakdown, and would be recommended in patients with concomitant hyperglycemia, especially with metabolic decompensation such as ketoacidosis." (PMID 37563290, 2023). "However, upregulation of LPL activity in beta cells has been shown to lead to hyperglycaemia during a glucose tolerance test." (PMID 29502266, 2018). "Hyperglycemia in mothers with GDM is a teratogenic condition that affects organogenesis and induce epigenetic changes primarily through insulin production, modifications Melanocortin 4 receptor, lipoprotein lipase, and leptin methylation patterns, and increased adiposity in the growing fetus." (PMID 40319278, 2025).
lipid metabolism disorders (18 papers, 2013 to 2025). "Liver LPL overexpression or deficiency has recently revealed glucose and lipid metabolic disorders in mice." (PMID 34128694, 2021). "Further, drugs that reduce lipid levels, such as fibrates, are useful for treating other lipid metabolism disorders, but are generally ineffective in cases with LPL deficiency." (PMID 31203594, 2019). "We found the association between LPL rs328 and disorders of lipid metabolism again in the European American adult analyses for both discovery and replication datasets (P = 2.8 × 10-3 and 9.91 × 10-5, respectively)." (PMID 27535653, 2016). "As a key regulator of lipid metabolism, LPL may play a core role in lipid metabolism disorders associated with DKD." (PMID 40747306, 2025). "Mutations located in the LPL gene can cause hyperlipoproteinemia and lipid metabolism disorders." (PMID 36904157, 2023). "Polymorphisms and mutations in LPL have been associated with lipid metabolism disorders." (PMID 23634756, 2013). "By regulating the activity of LPL, these drugs are expected to not only alleviate lipid metabolism disorders but also improve the pro-inflammatory immune environment in the kidneys, reduce persistent tissue damage, and ultimately delay the progression of DKD." (PMID 40747306, 2025). "The enrichment of LPL genes in these pathways supports previous findings and further highlights its key role in regulating lipid metabolism disorders in DKD." (PMID 40747306, 2025). "When IR occurs, the synthesis of lipoprotein lipase in the body is reduced, which in turn reduces the hydrolysis of TG, which leads to lipid metabolism disorders." (PMID 37601073, 2023). "For instance, total flavonoids from Ligustrum lucidum were shown to have a beneficial regulatory effect on lipid metabolism disorder in rats in a high-fat model, possibly via regulation of the PPARα-LPL pathway and HMGCR expression." (PMID 31714944, 2019). "Among them, Ibrolipim showed a high interaction score, indicating that it may alleviate lipid metabolism disorders and related inflammatory responses in DKD by regulating LPL activity." (PMID 40747306, 2025). "This study systematically identified the lipoprotein metabolism-related gene LPL as a hub gene in DKD through bioinformatic analysis and immunohistochemical validation, revealing its multiple roles in lipid metabolism disorders and immune-inflammatory response regulation." (PMID 40747306, 2025). "Therefore, the reduction of LPL and the increases in ABC proteins could mediate the lipid metabolic disorders in Rubiconad−/− mice." (PMID 32811819, 2020). "Meanwhile, in our study, POE reduced the expression of miR-122, acetyl coenzyme A carboxylase (ACC) 1 mRNA and protein and increased the expression of lipoprotein lipase (LPL) mRNA and protein in liver, which indicated that POE could improve the lipid metabolism disorder induced by ethanol." (PMID 31398934, 2019).
Alzheimer disease (15 papers, 2012 to 2025). A progressive, neurodegenerative disease characterized by loss of function and death of nerve cells in several areas of the brain leading to loss of cognitive function such as memory and language. "Genetically predicted LPL activation was significantly associated with increased risk of Alzheimer’s disease in FinnGen (OR = 1.47, 95% CI=1.24 to 1.74, P=7.6e-06)." (PMID 40052268, 2025). "LPL is generally thought to be neuroprotective, and polymorphisms have been associated with Alzheimer disease." (PMID 36721240, 2023). "Although the precise function of LPL in the brain remains to be determined, several studies have implicated LPL variants in Alzheimer’s disease (AD) risk." (PMID 33172164, 2020). "In Study D, an association with borderline significance was found between the HindIII polymorphism in LPL and late-onset Alzheimer’s disease (P=0.048)." (PMID 26199897, 2015). "LPL hydrolyzes circulating chylomicrons and very-low-density lipoprotein, is a regulator of brain energy balance, is strongly expressed in the hypothalamus, hippocampus, and striatum, and LPL variants are associated with neurite pathology and Alzheimer disease." (PMID 34504056, 2021). "Therefore, it is important to understand the range of differences in LPL levels and function in human brain, particularly because LPL polymorphisms have been implicated in pathogenesis of stroke, Alzheimer’s disease, schizophrenia and other brain disorders." (PMID 24004859, 2013). "Full elucidation of the role of LPL in Alzheimer’s disease will require further research beyond these genetic analyses." (PMID 40052268, 2025). "Contrasting our results, other studies have shown a potential protective effect of LPL activation on Alzheimer’s disease." (PMID 40052268, 2025). "scRNA-seq of DAM, in a murine model of Alzheimer’s disease (AD), revealed that LPL levels are markedly increased in a unique microglial subset associated with phagocytosis and protection in AD." (PMID 34122343, 2021). "Reduced lipoprotein lipase levels have been observed in the CNS of patients with Alzheimer’s disease (AD)." (PMID 35052526, 2021). "We evaluated LPL distribution in healthy and Alzheimer’s disease (AD) brain tissue and its relative levels in cerebrospinal fluid." (PMID 24004859, 2013).
Stroke (14 papers, 2007 to 2025). Sudden impairment of blood flow to a part of the brain due to occlusion or rupture of an artery to the brain. "Variations of the LPL gene can alter its enzymatic properties and activity role, especially as a stroke risk factor." (PMID 34445740, 2021). "This meta-analysis investigated the association of rs285 and rs320 LPL polymorphism with stroke risk." (PMID 30140409, 2018). "When the association analysis in studies with sample sizes less and more than 500 participants was performed, we observed the same significant protective association between LPL-HindIII and stroke risk." (PMID 30140409, 2018). "Our study revealed that LPL-HindIII is a protective factor against stroke risk in all of the five genetic models (P<0.05)." (PMID 30140409, 2018). "In this study, the association of rs285 and rs320 polymorphisms in the lipoprotein lipase gene with stroke risk was evaluated by meta-analysis." (PMID 30140409, 2018). "This meta-analysis indicated that risk of stroke was decreased in rs320 and rs285 polymorphisms in the LPL gene." (PMID 30140409, 2018). "Several studies have evaluated rs320, rs285 y rs328 polymorphisms in the lipoprotein lipase gene and their association with stroke." (PMID 28293042, 2016). "This meta-analysis suggests that the LPL-HindIII and LPL-PvuII polymorphisms may alter the risk of stroke." (PMID 30140409, 2018). "Regarding LPL-PvuII polymorphism, we also observed a protective effect against the stroke risk." (PMID 30140409, 2018). "In addition, the association between LPL-HindIII and stroke risk was further stratified by stroke subtypes, HWE status, country, and sample size." (PMID 30140409, 2018). "Polymorphism in several genes such as lipoprotein lipase (LPL) is propounded as a risk for stroke." (PMID 30140409, 2018). "Some polymorphism in the lipoprotein lipase gene may play a role as risk or protection factors for stroke onset." (PMID 28293042, 2016). "The analysis of LPL polymorphisms rs320, rs285 and rs328 and the study of their distribution among Colombian population becomes the first study in Colombia to evaluate their association with stroke development." (PMID 28293042, 2016). "We hypothesize that polymorphisms (rs320, rs285 and rs328) located in the lipoprotein lipase gene acts as exposure markers for development of stroke in Colombian population." (PMID 28293042, 2016). "Therefore, any variations in the protein and RNA sequence of LPL may change the enzyme activity and subsequent stroke susceptibility." (PMID 30140409, 2018). "Polymorphisms in several genes such as PRKCH (OMIM: 605437), PITX2 (OMIM: 601542), ZFHX3 (OMIM: 104155), ALOX5AP (OMIM: 603700), HDAC9 (OMIM: 606543), ALDH2 (OMIM: 100650), NLRP3 (OMIM: 606416), MMP9 (OMIM: 120361), and LPL (OMIM: 609708) may be related to the risk of stroke." (PMID 30140409, 2018). "ApoA-V stimulates the activity of LPL; thus, a decrease in its plasma concentration leads to an increase in TG, which accelerates atherosclerosis and plaque formation that, if ruptured, can lead to strokes." (PMID 40869228, 2025). "Interestingly, F4/80+, M-CSF+ and LPL+-cells frequently engulfed both oligodendrocytes and whole neurons after stroke." (PMID 35177618, 2022). "LPL gene polymorphisms are not genetic markers for the development of stroke in the Colombian sample used." (PMID 28293042, 2016). "LPL+;GFP+ cell density was also lower in VPS35CX3CR1 mice than that of control mice in response to the stroke injury." (PMID 31771656, 2019). "We found a decrease in LPL+ DAM, but an increase in CD206+ microglia (anti-inflammatory-like), in VPS35 mutant cortex after stroke." (PMID 31771656, 2019). "However, the current study shows that the difference in the distribution of rs320, rs285 y rs328 polymorphisms in lipoprotein lipase gene, in patients with stroke and healthy population, do not act as statistically significant risk markers for stroke development in the our population." (PMID 28293042, 2016).
Stroke (continued). "Several genes involved in lipid metabolism such as Paraoxonase (PON), Lipoprotein Lipase (LPL) and Fatty Acid-Binding Protein 2 (FABP2) have been examined in the stroke populations." (PMID 17553166, 2007).
chronic lymphocytic leukemia (13 papers, 2014 to 2025). "Recently, studies have implicated LPL as a biomarker for poor prognosis in chronic lymphocytic leukaemia." (PMID 34976793, 2021). "For instance, in chronic lymphocytic leukemia, LPL expression correlates with adverse clinical outcomes, although its precise functional roles and regulatory mechanisms remain under investigation." (PMID 40625358, 2025). "HL, Hodgkin lymphoma; NHL, non-Hodgkin lymphoma; DLBCL, diffuse large B- cell lymphoma; SLL, small lymphocytic lymphoma; LPL, lymphoplasmacytic lymphoma; MCL, mantle cell lymphoma; MZL, marginal zone lymphoma; Compared by Chi square test." (PMID 39712508, 2024). "In chronic lymphocytic leukemia, lipoprotein lipase can cooperate with STXBP3 to promote chronic lymphocytic leukemia cells apoptosis." (PMID 33090721, 2020). "We and others described a link between the expression of LPL in the tumor cell and a poor clinical outcome of patients suffering Chronic Lymphocytic Leukemia (CLL)." (PMID 29206143, 2017). "Patients with high lipoprotein lipase mRNA expression in B-cell chronic lymphocytic leukemia (B-CLL) demonstrate significantly higher MTA3 signaling activity, which is associated with adverse cytogenetic profiles, shorter time to first treatment, and reduced overall survival." (PMID 41584603, 2025). "In fact, LPL is overexpressed in hepatocellular carcinoma, non-small cell lung cancer (NSCLC), and chronic lymphocytic leukemia (CLL)." (PMID 38339301, 2024). "A study reported that the use of the lipoprotein lipase inhibitor orlistat resulted in apoptosis of B-cell chronic lymphocytic leukemia (CLL) cells without killing normal B cells from donors." (PMID 33208446, 2021).
COVID-19 (12 papers, 2020 to 2025). A disease caused by infection with severe acute respiratory syndrome coronavirus 2. "Among the significantly up- or down-regulated proteins in COVID-19 patient urine, metallothionein-1G, lipoprotein lipase, β2M, PRKACA, FOLR2, and APOA4, showed significant changes compared to both healthy controls and non-COVID-19 pneumonia cases." (PMID 33203833, 2020). "This suggests that during COVID-19, Apo C-III would be more associated with TRLs, and could inhibit their catabolism via its function as a lipoprotein lipase inhibitor." (PMID 36902035, 2023). "In our case, an increase in PLTP and a decrease in LPL in COVID-19 samples were observed; however, the possible impacts on lipid composition are unknown." (PMID 37628421, 2023). "Several cytokines and inflammatory mediators that are overexpressed during COVID-19 may interact directly with LPL or its regulatory proteins, such as apo CII23." (PMID 33785815, 2021). "Several cytokines and inflammatory mediators overexpressed during COVID-19 may directly or indirectly inhibit the activity of lipoprotein lipase (LPL), a key enzyme in lipid metabolism." (PMID 34124081, 2021). "Recent studies show COVID-19 convalescents had a higher level of CETP than the healthy cohort and lipoprotein lipase was impaired by the elevated IL-6 and TNF-α in addition to increased hepatic lipase in the LC cohort." (PMID 40335840, 2025). "The mechanisms of COVID-19-induced increased triglyceride (TG) levels are not fully understood but are hypothesized to be related to hemophagocytic lymphohistiocytosis (HLH) syndrome, acquired lipoprotein lipase (LPL) inhibitors, liver failure, or as a side effect of medications." (PMID 38979030, 2024).
Glucose intolerance (12 papers, 2010 to 2025). Glucose intolerance (GI) can be defined as dysglycemia that comprises both prediabetes and diabetes. "LPL deficiency is associated with increased ceramide levels in the hypothalamus, in addition to increased body weight and glucose intolerance." (PMID 34069652, 2021). "With age, LPL-deficient mice were found to display glucose intolerance and decreased first-phase insulin secretion." (PMID 23186339, 2012). "The depletion of LPL in the VMH induced body weight gain in mice associated to hyperinsulinemia and glucose intolerance as well as a decrease in locomotor activity." (PMID 31474875, 2019). "Last, the specific depletion of LPL in astrocytes reduced the accumulation of lipid droplets in these cells, increased body weight and induced a glucose intolerance in these high-fat diet fed-mice." (PMID 31474875, 2019). "However, high carbohydrate diets are known for their hypertriglyceridemic effects and glucose intolerance which appear to be due to downregulation of muscle lipoprotein lipase (LPL) activity." (PMID 20671994, 2010).